AEN (apoptosis enhancing nuclease)
Description:
Exonuclease with activity against single- and double-stranded DNA and RNA.
Synonyms: ISG20L1; FLJ12484; FLJ12562; pp12744
Tractability: PROTAC: ubiquitination databases record sites on it.
Gene: Protein-coding gene on chromosome 15 (88,620,070 to 88,632,281, forward strand). Ensembl gene ENSG00000181026.
Subcellular location: Nucleus; Nucleus, nucleolus
Subcellular location (Human Protein Atlas): Nucleoli; Nucleoplasm
Gene Ontology:
Molecular function: DNA exonuclease activity; exonuclease activity; protein binding; nucleic acid binding
Biological process: response to ionizing radiation; RNA processing
Cellular component: nucleolus; nucleoplasm; nucleus
Genetic constraint (gnomAD): Loss-of-function variants: 21 observed, 18 expected, observed/expected ratio (o/e) 1.17, 90% interval 0.83 to 1.67. The upper end of that interval is the gene's LOEUF score, 1.67, which puts it in group 6 of 6, group 1 being the genes least tolerant of losing a copy. Missense variants: 462 observed, 447.24 expected, observed/expected ratio (o/e) 1.03, 90% interval 0.96 to 1.12. Synonymous variants: 190 observed, 178.88 expected, observed/expected ratio (o/e) 1.06, 90% interval 0.94 to 1.2.
Homologues: Orthologues: chimpanzee AEN (99% identical), macaque AEN (95% identical), pig AEN (84% identical), dog AEN (83% identical), guinea pig AEN (78% identical), rat Aen (75% identical), mouse Aen (72% identical), Drosophila melanogaster prage (25% identical), Caenorhabditis elegans pqe-1 (20% identical), zebrafish rexo1 (19% identical), zebrafish zgc:152968 (19% identical), Drosophila melanogaster CG12877 (18% identical). Paralogues in human: ISG20L2 (39% identical), ISG20 (29% identical), REXO4 (28% identical), REXO1 (21% identical), REXO5 (20% identical).
Diseases named in the same sentence as AEN in open-access papers:
AEN is named in the same sentence as 11 diseases in open-access papers, as found by Europe PMC text mining. Sharing a sentence is not in itself a finding about the gene and the disease. The quoted sentences say what the papers report.
colon cancer (1 paper, 2022). "By regression analysis, 6 immune-related DEGs (AEN, F2RL1, NR3C2, PPARGC1A, LGALS4, and XDH) were identified as potential prognostic factors, of which AEN, LGALS4, and XDH were used to construct a risk score model, which can effectively predict overall survival (OS) in colon cancer patients." (PMID 36589748, 2022).
Fraser syndrome (1 paper, 2024). Fraser syndrome is a rare clinical entity including as main characteristics cryptophthalmos and syndactyly.
multiple myeloma (1 paper, 2021). "Among all dysregulated immune-related mRNAs, AEN, CD320, FABP5, and GPI were risk factors for multiple myeloma, while CXCL12, IGKC, NOD2, VCAM1, and WNT5A were protective factors for multiple myeloma." (PMID 34249967, 2021).
virus infection (1 paper, 2023). "MARC-145 cells were then transfected with increased doses of Flag-AEN before virus infection and the inhibitory effects on PEDV N protein production and viral titers were observed in a dose-dependent manner." (PMID 38251332, 2023).
cancer (4 papers, 2021 to 2023). A tumor composed of atypical neoplastic, often pleomorphic cells that invade other tissues. "In addition to known cachexia genes such as FOXO1, novel genes from muscle, including PPP1R8 and AEN correlated with cancer weight loss." (PMID 33923976, 2021). "Comparing the total expression differences of the three target genes in all cells of cancer tissue and normal tissue, the results suggest that: AEN gene expression is higher in cancer tissue than normal tissue, while LGALS4 and XDH gene expression is lower in cancer tissue." (PMID 36589748, 2022).
tumor (2 papers, 2020 to 2021).
infection (1 paper, 2023). The state of being infected such as from the introduction of a foreign agent such as serum, vaccine, antigenic substance or organism. "Considering that Vero cells are also African green monkey kidney cells and a good cell model for the in vitro study of PEDV, and most importantly, they are type I IFN-deficient cells, AEN and AEN-4A were overexpressed in Vero cells to verify the antiviral effect after infection with PEDV." (PMID 38251332, 2023). "The results show that the production of PEDV N protein significantly decreased upon AEN overexpression at 12 and 24 h post-infection." (PMID 38251332, 2023). "The mRNA levels of AEN were significantly upregulated 1.7-, 6.9-, and 16.5-fold at 12, 24, and 36 h post infection, respectively, compared with that of uninfected MARC-145 cells." (PMID 38251332, 2023).
AEN also shares sentences with these, for which no sentence is quoted: Alzheimer disease (1 paper); radiation injury (1); rhabdomyosarcoma (1); schizophrenia (1).